NFAT5 (nuclear factor of activated T cells 5)
Diseases named in the same sentence as NFAT5 in open-access papers (continued):
Sharing a sentence is not in itself a finding about the gene and the disease.
tumor (continued). "It plays an important role in the occurrence and development of various human tumor diseases, and studies have shown that NFAT5 can regulate the transcription of the mouse TERT gene and promote the expression of TERT." (PMID 35739589, 2022). "Towards this, we determined the NFAT5 expression in the tumor-infiltrating CD4+T cells following a salt-modified diet." (PMID 35741331, 2022). "Our data suggested that, while anti-CTLA4-mediated-specific anti-tumor response was maintained by NFAT5 knock out, non-tumor-specific (generalized) salt-mediated NLRP3 pro-inflammatory responses were abrogated by NFAT5 knock out." (PMID 35741331, 2022). "Next, we wanted to determine if NFAT5 knock out reduced the anti-CTLA4-mediated anti-tumor activation of CD4+T cells." (PMID 35741331, 2022). "For instance, suppression of TTN-AS1 resulted in an ability inhibition of OSCC cells in the tumor growth and metastasis via miR-411-3p/NFAT5 axis." (PMID 34336002, 2021). "As expected, NFAT5-KO in CD4+T cells had significantly lower tumor localization with effector phenotype." (PMID 33918403, 2021). "Using a transgenic murine model, we demonstrated that CD4 specific TonEBP/NFAT5 knock out (CD4cre/creNFAT5flox/flox) abrogated the induction of the effector phenotype and anti-tumor efficiency of CD4+T cells following high salt treatment." (PMID 33918403, 2021). "Overall, these results demonstrate that hyperosmotic stress contributed to the activation of DPAGT1 and the subcellular translocation of EGFR via NFAT5 induction in the tumor microenvironment." (PMID 32901097, 2021). "NFAT5-deficient macrophages had reduced pro-inflammatory status, followed by the reduced infiltration of cytotoxic CD8+ T cells into the tumor and the enhanced tumor growth of LLC and ID8 ovarian carcinoma models." (PMID 32486098, 2020). "The gene expression of NFAT5 is downregulated in ccRCC samples compared to normal tumor samples as well as expression of NFAT5 target genes." (PMID 32059438, 2020). "ETBF-induced tumor growth was significantly decreased by knocking down NFAT5, and these effects were reversed by JMJD2B adenovirus transduction in CRC-bearing nude mice." (PMID 32684087, 2020). "For the in vivo study, we administered a lentivirus carrying NFAT5 siRNA under the Ly-6C promoter (NFAT5 siRNA-LV) or control siRNA-LV intravenously into 4T1 or B16F10 tumour-bearing mice every 2 days for 16 days." (PMID 32265505, 2020). "Tumor tissue manifested a higher staining score, and patients with increased NFAT5 had a poorer prognosis." (PMID 31827081, 2019). "NFATC1, NFATC2, NFATC3, NFATC4, and NFAT5 were all highly expressed in the tumor tissue of the TCGA dataset compared with normal tissue of the GTEx dataset." (PMID 31827081, 2019). "We then performed CCK8 assays and colony formation assays to evaluate the pro–proliferation effect of NFAT5 on tumor cells." (PMID 31827081, 2019). "Accordingly, NFAT5, a representative osmo-sensitive transcription factor, has been proposed to mediate tumor progression." (PMID 30873159, 2019). "Aberrant high expression of NFAT5 inhibits tumor proliferation and progression by dampening its Warburg effect, which is partly caused by transactivation of PGK1." (PMID 31827081, 2019). "The result showed that NFAT5 was significantly correlated with tumor size, tumor differentiation, lymph node metastasis, distant metastasis, and TNM stage." (PMID 31827081, 2019). "Intriguingly, NFAT5-deficient macrophages show the reduced infiltration of effector CD8+ T cells into the tumor site, which is accordant with our findings of NFAT5 regulation of FLS migration." (PMID 30873159, 2019). "The results indicated that the mRNA and protein expression of NFAT5 was low in liver tumor tissues, but high in corresponding para-tumor tissues." (PMID 29052520, 2017). "The key finding of the current study is that NFAT5 acts as a tumor suppressor by inhibiting cell cycle progression and promoting tumor cell apoptosis in vitro." (PMID 29052520, 2017).
tumor (continued). "The expression of NFAT5 was examined via immunohistochemical staining of 90 pairs of liver tumor tissues/corresponding para-tumor tissues using antibodies against NFAT5." (PMID 29052520, 2017). "For instance, degradation of NFAT5 is induced in cardiomyocytes treated with doxorubicin, a commonly used anti-tumor agent, and a concurrent decrease of NFAT5 exacerbates myocyte death upon doxorubicin treatment." (PMID 29220410, 2017). "To define the roles of NFAT5 and SBF2-AS1 in tumor growth ability in vivo, we established mouse xenograft models with NFAT5 knockdown, SBF2-AS1 knockdown and NFAT5 and SBF2-AS1 dual-knockdown GBM cells by subcutaneous injection." (PMID 28983240, 2017). "NFAT5 is a crucial component in tumor development and progression, particularly in regulating inflammation in the carcinogenesis process." (PMID 28871224, 2017). "The results showed that NFAT5 expression was reduced in liver tumor tissues compared with expression in para-tumor tissues." (PMID 29052520, 2017). "Additionally, NFAT5 regulates S100A4, an essential protein linked to tumor metastasis, through an integrin-dependent mechanism." (PMID 40421201, 2025). "Additionally, we examine the role of NFAT5 in contributing to the varying responses of these cell types, with the goal of elucidating the mechanisms governing tumor cell behavior under hyperosmotic conditions." (PMID 41584586, 2025). "Similarly, lncRNA MFI2-AS1, enriched in NSCLC-derived exosomes, sponges miR-107, increasing NFAT5 expression and promoting tumor progression." (PMID 40421201, 2025). "Indeed, deletion of NFAT5 in a CD4 promoter-driven Cre-Lox recombination system improves tumour control by tumour-specific T cells in a mouse model of melanoma." (PMID 39399500, 2024). "Moreover, stronger fluorescence signal of O6-MetG was observed in mice bearing NFAT5 K668R transfected U87/EGFRvIII tumors, compared to NFAT5 WT tumor cells." (PMID 37429858, 2023). "DDX17 and DDX5 may play a critical role in tumor cell migration by simultaneously regulating the transcriptional activity and AS of NFAT5 in HeLa cells." (PMID 36164607, 2022). "PC2 (driven by Ptgs2, Ptges, Inhba, Tacstd2, and Nfat5) could help distinguish between tumor and healthy, although in the Parsortix samples, healthy falls between the two tumor conditions on the PC1 axis." (PMID 35153760, 2021). "The reverse correlation in the expression levels of miR-20b and its target genes suggests that the tumour-suppressive function of miR-20b in thymoma could be due to its inhibition of NFAT signalling by the repression of NFAT5 and CAMTA1 expression." (PMID 34064510, 2021). "Hypoxia, ROS, and angiogenesis occur in inflamed lesions and tumor microenvironments, and exploring how NFAT5 responds to these stimuli could help understand its role in the communication between immune and non-immune cells at these sites." (PMID 30949179, 2019). "Recent studies have pointed to an important role for NFAT5 in modulating tumor biology." (PMID 28983240, 2017). "Knockdown of NFAT5 in GBM cell lines inhibited tumor-driven angiogenesis." (PMID 28983240, 2017). "However, if cells of a growing tumor invade the renal medullary region, these cells are exposed to hyperosmotic conditions, which means that NFAT5 activity is increased." (PMID 25152734, 2014). "Thus, strong NFAT5 expression could indicate an activated immune response that curtails tumor aggressiveness and consequently tapers down the tempo of metastatic spread." (PMID 38558282, 2024). "NFAT5 may therefore promote tumor cell migration, leading to the formation of various new tumors." (PMID 29052520, 2017). "Inhibition of both molecules reduces proliferation and migration, while NFAT5 overexpression enhances AQP5 expression, fostering tumor cell growth." (PMID 40421201, 2025). "The role of NFAT5 in HCC remains controversial; NFAT5 functions as a tumor suppressor by promoting PARP-1- and Bax/Bcl-2-dependent apoptosis." (PMID 40421201, 2025).
tumor (continued). "miR-194 binds to the 3’-UTR region of NFAT5, reducing NFAT5 expression and protein abundance in high-glucose-induced NSCLC cells, linking metabolic dysregulation to tumor progression." (PMID 40421201, 2025). "Elevated NFAT5 expression increases the expression of gluconeogenesis-related genes GLUT1 and PGK1, leading to enhanced aerobic glycolysis, proliferation and tumor metastasis in ICC.METTL3 is a poor prognostic factor for ICC patients." (PMID 39289775, 2024). "This immune response reduced the levels of CD3d, IL-2, IL-2 receptor chain alpha, forkhead box O1 (FOXO1), and nuclear factor of activated T cells 5 (NFAT5); a microenvironment that supports tumor progression." (PMID 36226048, 2022). "The aim of this study was to determine NFAT5 expression in the hyperosmotic OSCC tumor microenvironment and show how NFAT5 affected OSCC cell behavior, such as tumor progression." (PMID 32901097, 2021). "The other pro-inflammatory genes, nuclear factor of activated T-cells 5 (NFAT5), enhance pro-inflammatory macrophage polarization when appropriately stimulated and would be neutralized in a pro-M2 tumor microenvironment." (PMID 34579246, 2021). "Lastly, in order to make the newly obtained knowledge easily accessible to experimental immunologists, we showed the expression of NFAT5, IL2RA, CCR8, BCL6, and KCNK5 in the tumor-infiltrating T cells in a flow cytometric format." (PMID 30061879, 2018). "Conversely, in Caki-1 cells, high salt did not significantly impact proliferation, tumor growth, or NFAT5 expression." (PMID 41584586, 2025). "NFAT5 binds to DARS2, suppressing its expression and thereby supporting tumor suppression." (PMID 40421201, 2025). "Furthermore, defects in DNA repair and damage response genes such as RAD51, KU80 SIRT1, NFAT5, and REV3L, or ESCC tumor cells expressed higher CLDN4 to harbor stem-like properties are also the potential CCRT resistance mechanisms." (PMID 35457185, 2022). "However, lncRNA SBF2-AS1 (SBF2 antisense RNA 1), which is upregulated by NFAT5 in glioblastoma cells, can sponge miR-338-3p to release the inhibition of EGFL7 and subsequently stimulate angiogenesis in tumours." (PMID 34064510, 2021). "As expected there was no expression of NFAT5 at the end of three high salt stimulation cycles in the CD4+T cells obtained from day 21 DLNs of tumor bearing CD4+NFAT5-KO mice." (PMID 33918403, 2021). "Although for genes like Il15 we did not observe any difference between healthy and tumor-bearing mice in Ficoll or Parsortix samples; others, such as Egr1, Zc3h12a, Klf4, or Nfat5, allowed distinguishing for cancer or CTC presence." (PMID 35153760, 2021). "In vivo intraperitoneal injection of CD4+T cells from DLNs of CD4+NFAT5-KO (following three high salt stimulations) into day 21 orthotopic syngeneic tumors in wild type mice demonstrated a lack of anti-tumor response." (PMID 33918403, 2021). "In addition, knockdown of TLR4 downregulated NFAT5, JMJD2B, and NANOG expression in the xenograft tumor tissues." (PMID 32684087, 2020). "Furthermore, western blotting confirmed that knockdown of NFAT5 suppressed ETBF stimulated-JMJD2B and NANOG expression in the xenograft tumor tissues, and the NANOG decrease was efficiently rescued by JMJD2B overexpression." (PMID 32684087, 2020). "Interestingly, we have identified several transcription factors like TRPS1, NFAT5, FoxF2, ELF4, RLF etc. which haven’t previously been reported to be involved in PDAC but shown to induce EMT, angiogenesis or proliferation of tumours in other organs." (PMID 31795960, 2019). "We first examined messenger RNA (mRNA) expression of NFAT family members (NFATc1, NFATc2, NFATc3, NFATc4, and NFAT5) in 30 pairs of HCC tumor tissues (T) and corresponding adjacent nontumor tissues (NT) by qRT‐PCR." (PMID 30085405, 2018).
tumor (continued). "NFAT5/TonEBP/OREBP is the only known osmotic pressure-sensitive transcription factor in mammals and plays a vital role in enhancing cell survival, migration and proliferation, vascular remodeling, tumor invasion and angiogenesis." (PMID 29052520, 2017). "NFAT5’s involvement in cancer pathogenesis is not as extensively studied as other transcription factors; however, there is evidence suggesting its potential impact on tumor development." (PMID 38612478, 2024). "Besides the direct regulation of Nfat5 by miRNA, titin-antisense RNA 1 (TTN-AS1), also known as a tumour promoting lncRNA, could act as a miR411-3p sponge to indirectly regulate cell proliferation and migration." (PMID 34064510, 2021). "In our analyses, NFAT5 and DPAGT1 protein expression was upregulated in the cells of the xenografts under a hyperosmotic cancer microenvironment, and contributed to the enhancement of the progression and invasion of cancer cells of the tumor mass formed by transplanted HSC-3 cells." (PMID 32901097, 2021). "Together, in a sharp contrast to the tumorigenic role of NFAT5 in the cancer cells, NFAT5 in immune cells seems to escalate antitumor immunity by polarizing pro-inflammatory macrophages as well as promoting accumulation of CD8+ T cells adjacent to tumor masses." (PMID 30873159, 2019). "Since this region is not exposed to hyperosmotic stress, even during antidiuresis, osmolality-induced increase of cellular NFAT5 activity may be not relevant as long as tumor cells remain in the cortex." (PMID 25152734, 2014). "However, it cannot be ruled out that other NFAT5 target genes also stimulate tumor development and metastasis." (PMID 25152734, 2014). "In this context, the initially described tumor-suppressive and anti-invasive properties of TRPM1 have recently been shown to be executed by its intronic miR-211 (and not by TRPM1 itself) via down-regulation of the miR-211 direct and indirect targets TGFBR2, NFAT5, and IGF2R." (PMID 24039954, 2013). "We also found strong negative correlations between the expression of NFAT5 and the four predicted miRNAs in RCC tumor samples and other types of cancer." (PMID 31756931, 2019). "Similarly, miR-338-3p also does not target Nfat5; instead, it targets EGF-like domain 7 (EGFL7), a gene potentially promoting tumour cell growth." (PMID 34064510, 2021).
cancer (49 papers, 2010 to 2025). A tumor composed of atypical neoplastic, often pleomorphic cells that invade other tissues. "As an important regulator of both innate and adaptive immunity, NFAT5 is also implicated in the pathogenesis of various diseases, including various inflammatory diseases and cancer development (13, –, 18)." (PMID 37227295, 2023). "NFAT5, a pleiotropic stress protein also mediates metabolic reprogramming in several immunological disorders and is associated with cancer development and progression in numerous entities." (PMID 34233711, 2021). "In this study, we found that NFAT5 was upregulated in OSCC cancer cells in association with the upregulation of DPAGT1." (PMID 32901097, 2021). "Collectively, these data suggested that triggering autocrine TNF production via hypertonicity-induced p38/NFAT5 activation was underlying synergistic cancer cell killing of SM/NaCl combinations." (PMID 28771230, 2017). "We demonstrated the presence of a clearly positive correlation between the level of NFAT5 protein expression and OS in patients with HBV-associated HCC, suggesting that NFAT5 is a cancer suppressor gene." (PMID 29052520, 2017). "A deeper understanding of the molecular mechanisms underlying NFAT5 involvement in these processes could uncover new therapeutic strategies aimed at targeting NFAT5 to restrain cancer progression." (PMID 40421201, 2025). "Furthermore, integrin-induced transcriptional activity of TonEBP/NFAT5 causes cancer cell metastasis." (PMID 38438872, 2024). "NFAT5 is a mRNA and it has been reported to be associated with several cancers." (PMID 32863773, 2020). "For example, NFAT5 has been implicated in cancer cell proliferation and invasion." (PMID 32802855, 2020). "Furthermore, the possible role of NFAT5 in cancer is supported by the fact that genes encoding proteins involved in the transport of osmoregulators are markers of the cancer phenotype." (PMID 31756931, 2019). "The osmosensitive transcription factor NFAT5 has been associated with a variety of cancers." (PMID 25152734, 2014). "However, the mechanism underlying the regulation of NFAT5 nuclear translocation and protein stability during cancer progression, especially upon growth factor stimulation, remains unclear." (PMID 37429858, 2023). "This section explores the role of NFAT5 in cancer initiation and progression, shedding light on its complex functions in various cancer types." (PMID 40421201, 2025). "Despite these limitations, our findings underscore the critical role of osmotic stress tolerance in cancer cell behavior and support the need for further exploration of NFAT5 and related osmo-adaptive pathways as potential therapeutic targets." (PMID 41584586, 2025). "We first found that NFAT5 protein, which is known to be expressed in various cell types, including those of the kidney, cancer cells, and immune cells, was also expressed in the intestinal epithelium of WT mice." (PMID 40663408, 2025). "NFAT5 is required for the survival and proliferation of diverse types of cells, including kidney epithelial cells, cancer cells, T cells, and macrophages." (PMID 40663408, 2025). "In contrast, in vertebrates, NFAT5 plays a role in more complex immune regulation, including cell death, immune tolerance, and its involvement in chronic inflammation and cancer." (PMID 40076009, 2025). "Collectively, our results, supported by prior evidence, underscore the essential role of NFAT5 in promoting cell viability under hyperosmotic conditions, a critical function observed in both normal renal tissue and cancer cells." (PMID 41584586, 2025). "This highlights the multifaceted role of NFAT5 in cancer, influencing immune evasion, cell survival, proliferation, inflammation, and metastasis." (PMID 40421201, 2025). "Given the hypoxia-sensitivity of NFAT5 expression, we posit that local hypoxia of advanced cancer tissue contributes to or even accounts for upregulation of NFAT5 expression in EnCa." (PMID 38612478, 2024).